CD4 (CD4 molecule)
Diseases named in the same sentence as CD4 in open-access papers (continued):
Sharing a sentence is not in itself a finding about the gene and the disease.
influenza (continued). "Interestingly, both the exposure of PBMCs to 500 nm and 3 μm influenza conjugates resulted in a significant increase in the frequency of CD4+ T cells producing IFNγ and TNFα and in total amounts of these cytokines compared to exposure of PBMCs to unconjugated particles." (PMID 35890185, 2022). "Although sterilizing immunity to influenza is provided by neutralizing antibodies, the development of high affinity, class-switched antibodies is dependent on follicular helper cells, which are a subset of CD4 T cells elicited by both infection and vaccination." (PMID 35215193, 2022). "In addition, the group adoptively transferred young polyclonal CD4+ T cells into young and aged mice one day prior to influenza infection, and the analysis performed 14 dpi revealed an enhanced differentiation of the donor cells toward a TFR cell phenotype in aged mice." (PMID 36016952, 2022). "Interestingly, we observed that influenza-specific CD4+ T cell lung responses were more pronounced in individuals not colonized with S. pneumoniae at the time of vaccination, suggesting increased immunogenicity of LAIV in the absence of pneumococcal colonization." (PMID 33497364, 2021). "However, few studies have aligned the major histocompatibility complex (MHC) class II epitope sequences with the current vaccine strain or have phenotypically analyzed influenza-specific CD4 T cell responses at baseline and earlier than day 7 after vaccination." (PMID 34795301, 2021). "Notably, compared to a modest increase in CD8+/CD4+ T cell ratio induced by IL-2 treatment in the model of influenza infection, the same treatment in acute LCMV infection led to an approximately 3-fold increase in the CD8+/CD4+ T cell ratio in both spleen and inguinal lymph nodes." (PMID 34618873, 2021). "It is worth noting in this context that HA118-132-specific CD4 T cells displayed an antigen-experienced memory phenotype in all individuals, regardless of the vaccination history, suggesting that all individuals had been exposed to an influenza strain carrying this HA peptide." (PMID 34795301, 2021). "Thus, it is equally conceivable that such a mechanism might result in insufficient uptake of antigens by antigen-presenting cells (APCs) and subsequently reduced presentation via MHC class II to influenza-specific CD4 T cells." (PMID 34795301, 2021). "Thus, we next examined AT2 in vivo flu peptide/MHCII complex formation, by co-culturing in vivo-infected AT2s from wild-type or MHCII−/− B6 mice taken 4 days post influenza infection with polyclonal splenic CD4+ or CD8+ T cells taken 9 days post-infection, in the presence of soluble anti-CD28." (PMID 34183650, 2021). "In addition, activation patterns of vaccine-induced, influenza-specific CD4 T cell responses correlate with vaccine-elicited antibody titers and baseline factors that might be able to predict the cellular and humoral response to the vaccine are observed." (PMID 34795301, 2021). "Furthermore, we found that there was a trend (P = 0.0727) of increased TIGIT expression on pTfh cells in IL-21–treated animals, and influenza HAI titers day 14 after B1 correlated with both TIGIT+CD4+ Tcm (r = 0.6808, P = 0.0120) and TIGIT+ pTfh (r = 0.7387, P = 0.0112) cells." (PMID 34491910, 2021). "The most immunogenic of these epitopes, M1129-142-GLI, was able to stimulate cognate CD4+ T cell populations in culture that were larger in magnitude and exhibited greater avidity for HLA multimers across all donors than the well-studied HLA class II influenza epitope HA306-318-PKY." (PMID 32668259, 2020). "Although decreased CD4+ T cells in severe influenza patients was thought to be associated with aspergillus infection in a study with small sample, our data do not support the association between decreased CD4+ T cells and the occurrence of influenza associated aspergillosis." (PMID 33537328, 2020).
influenza (continued). "Finally, a subset of cytolytic CD4+ T cells have been shown to be protective in influenza and could serve as an additional avenue to boost the immune response." (PMID 33310880, 2020). "When the frequency of CD4 T cells producing IFNγ, IL-2, or TNFα was individually quantified for each of the proteins, the pediatric population had a higher frequency of influenza-specific CD4 T cells producing TNFα compared to IFNγ across all conditions examined." (PMID 30692574, 2019). "Studies have shown that older subjects experience altered frequencies of influenza-specific memory CD4+ T cell subsets post-vaccination relative to younger subjects, and these population shifts may alter the ability of memory T cells to effectively traffick to the lung in response to infection." (PMID 31528180, 2019). "However, whether the described tissue repair role of ILC2 in the lung is redundant with CD4+ T cell-derived AREG during influenza will require further investigation." (PMID 30893756, 2019). "Although imprinting in influenza immunity is most commonly discussed with regard to the B cell response, we propose here that imprinting may also have a dramatic impact on the specificity, phenotype and persistence of the CD4 T cell repertoire." (PMID 31134060, 2019). "Moreover, CD4+ T cell epitopes are relatively conserved across different influenza strains and TRM CD4+ cells may play a particularly important role in protecting against reinfection." (PMID 31700523, 2019). "In addition to considering the mechanisms that might underlie the CD4 T cell immunodominance of selected regions of HA, it is interesting to consider implications of these studies to human CD4 T cell immunity to influenza." (PMID 31694141, 2019). "The fact that we found impaired Mtb-specific CD4+ T cell responses and evidence for AAMs concomitant with increased Il10 expression in coinfected mice prompted us to determine the role of IL-10 receptor (IL-10R) signaling in influenza-induced exacerbation of Mtb infection." (PMID 30998505, 2019). "We point out however that protection from influenza disease correlates better with influenza-specific T-cell reactivity than antibody responses, and our results clearly show the effective role of both CD4 and CD8 cytotoxic cells in eliminating influenza virus from infected lung epithelium." (PMID 30641955, 2019). "Generated with CD4+ T help after naïve B cell precursors encounter their cognate antigen, the linked processes of differentiation (including Ig class switching) and proliferation also give rise to memory B cells, which then can change rapidly to ASC status after subsequent influenza encounters." (PMID 31312199, 2019). "Similarly, in animal models of influenza infection, recall of memory CD4 T cells specific for HA, but not NP, is associated with neutralizing antibody response to HA." (PMID 31694141, 2019). "Here, we demonstrate that males and females have different PBMC fractions of CD4+ T cells and NK cells, and that these differences mediate a significant part of the sex-differential expression levels in T cell and NK cell gene clusters after influenza vaccination." (PMID 30873150, 2019). "Furthermore, ex vivo restimulation of splenocytes from 2′FL-fed vaccinated mice by influenza-loaded BMDCs results in a higher proliferation of vaccine-specific CD4+ and CD8+ T-cell compared to control vaccinated mice, accompanied by a higher production of IFN-γ." (PMID 29593719, 2018). "Furthermore, in addition to helper functions, influenza-specific CD4+ T cells may be imperative to protection from heterologous influenza infection." (PMID 29587436, 2018). "Thus, influenza infection was shown to induce peripheral proliferation and accumulation of Ag-specific thymically derived Treg cells whereas conventional CD4+ T cells with identical specificity for the pathogen underwent little or no peripheral conversion in infected mice." (PMID 30455700, 2018).
influenza (continued). "Hence, the co-existence of local IgA and influenza-specific resident memory CD4+ T cells makes it difficult to identify the relative contribution each of these elements for protection, but ongoing studies in our laboratory is attempting to better dissect this question." (PMID 30271406, 2018). "Since our previous studies demonstrated Treg induction and suppression of adaptive T cell responses (decreased CD8+ IFNγ+ (Tc1) and CD4+ IFNγ+ (Th1) cells numbers) after exposure to EPFRs, we studied whether depletion of Tregs would restore the adaptive T cell response towards influenza." (PMID 28086957, 2017). "The evidence of pre-existing CD4+ T cell populations to influenza virus and their direct involvement in the in vivo elimination of virus-infected cells during primary and secondary infections have prompted Savic and colleagues to the development of an epitope-based universal influenza vaccine." (PMID 28289418, 2017). "To test whether Venuspos, antigen-bearing cells had the capacity to stimulate CD4 T cells, we isolated them based on differential expression of CD45 and HA using FACS, followed by co-culture with influenza-specific CD4 T cells, generated by in vivo peptide priming." (PMID 28883436, 2017). "Our previous work using a mouse model of secondary heterosubtypic influenza infection has shown that this competition results in a focusing of CD4 T cell response specificity towards internal virion proteins with a selective decrease in CD4 T cell reactivity to the novel HA epitopes." (PMID 28493882, 2017). "Moreover, for the IFN-γ+ CD4+ T-cell responses to a trivalent inactivated influenza vaccine in adults, the fold increases from the baseline after vaccination were previously shown to correlate inversely with the baseline responses, further confounding this observation." (PMID 28446441, 2017). "Our finding that antigen-specific effector CD4+ T cells upregulate the dual expression of IL-6Rα and IL-7R at late time points post influenza infection suggests that exposure to either cytokine could be a key determinant in further differentiation events and long-term cellular function." (PMID 26743592, 2016). "Taken together, these data support the hypothesis that the activation and differentiation of the aged NP-specific CD4+ T cells in response to influenza infection is impaired and results in lower numbers of GC TFH cells that may contribute to a deficient GC response." (PMID 27109638, 2016). "Importantly, high levels of IFN-γ production by memory CD4 T cells may also be critical for protection against influenza in humans, which implies a possible role for manipulating PD-1 pathway in vaccine regimens." (PMID 25803808, 2015). "Moreover, influenza-specific memory CD4+ T cells could be also recalled after the secondary challenge, while the antibody levels were unaffected." (PMID 26086392, 2015). "We first examined PBMC samples isolated from the five volunteers who had received the 2013–2014 influenza vaccine to identify the subsets of circulating CXCR5+CD4+ Tfh-like cellular populations as control experiments to determine whether different subsets could be identified." (PMID 26333070, 2015). "This may make PTB cases more at risk of influenza-associated mortality because of lower CD4+ T cell counts and not necessarily because of PTB." (PMID 26076197, 2015). "Although further studies are needed to assess the mechanisms of cell-mediated immunity with influenza vaccines, our results suggest that AS03-H5N1 vaccine may induce CD4+ T-cell responses that may be associated with long-term, heterosubtypic immune memory in children." (PMID 25652873, 2015). "In addition, the early change/increase of CD4+ T cell CD28 expression at Day 3 (relative to baseline) was significantly correlated with the observed increase in the influenza-specific B cell ELISPOT response at Day 28 post-vaccination compared to baseline (r = 0.216, p-value = 0.031)." (PMID 25816015, 2015).
influenza (continued). "Our data suggest that prophylactic oseltamivir treatment, although causing a marked reduction in influenza-related morbidity, inflammation, and effector CD8+ and CD4+ T cell responses, permits the generation of functional, long-lived, and cross-strain responsive memory CD8+ and CD4+ T cell pools." (PMID 26086392, 2015). "Therefore the magnitude of the influenza-specific CD4+ T-cell response enhanced by AS03 in the seasonal vaccine may be directly relevant to increasing protection against disease in older adults." (PMID 25078387, 2014). "Thus in human influenza-specific memory CD4 T cells, the IFNγ+ cells may variably express IL-2, but 2+γ- cells may include cells with a distinct differentiation state." (PMID 24788814, 2014). "For example IL-2,a critical regulator of Treg viability and maintenance, could potentially help sustain Treg responses in the late phase of influenza infection, with CD4+ T effector cells serving as a source of IL-2 through a CD86 engagement dependent mechanism." (PMID 25144228, 2014). "Thus, whereas antibody production is critical in the young to prevent primary influenza infection, CD4+ cells may be more important in immunologically experienced individuals undergoing heterosubtypic infection." (PMID 24690681, 2014). "Thus, CD25 deficiency impairs CD4 T cell numbers in the DLN and lung during influenza infection." (PMID 24586481, 2014). "Furthermore, CD4+ T cells could directly lead to severe immunopathology and tissue damage via a cytokine-independent manner in influenza infection." (PMID 24465940, 2014). "Thus, a shortened TIV-specific CD4 T cell response and increased expression of PD-1 on day 7 in aged subjects suggest a substantially altered boost of influenza-specific memory CD4 T cell in the aged compared to young subjects with potential implications for protective immunity." (PMID 24155927, 2013). "Furthermore, a single vaccination conferred protection against influenza that lasted at least 9 months, possibly indicating an initial CD4+ T cell contribution that could have facilitated the development of protective memory CD8+ T cells." (PMID 24244595, 2013). "Importantly, peptides enriched for non-cross-reactive A/California/04/09 specificities induced a higher proportion of Thpp-like IFNγ−IL-2+TNFα+ CD4 T cells than peptide pools cross-reactive with previous influenza strains, which induced more Th1 (IFNγ+TNFα+) responses." (PMID 23526940, 2013). "Furthermore we cannot rule out the possibility that in addition to their helper function, CD4+ T cells induced by the vaccine may have a direct effector function against subsequent influenza infection." (PMID 24204639, 2013). "Here we show that LACK158–173 influenza prime/boost immunisation resulted in considerable protection against Leishmania in a stringent mouse model of disease, and was associated with increased IFN-γ production by LACK158–173-specific CD4+ T cells in vaccinated animals." (PMID 22470440, 2012). "CD4 effector cells can also promote survival to a lethal dose of influenza infection and may contribute to immune-mediated pathology; CD4 effector T cells and memory contribute to immunity to influenza via multiple mechanism." (PMID 22393340, 2011). "We found that the quality of polyfunctional CD8 and CD4 effector/memory cells against influenza proteins (H3, H1, and NP) was similar at baseline in both arms of the study and thus confirmed the relative homogeneity of influenza-specific effector/memory cells before vaccination." (PMID 20520820, 2010). "Indeed, in some persons we also observed a significant decrease at t1 in CD4 T cells specific for vaccine preparation (donors 2, 16, 23, 27, 30, 31, 35, 41), specific for influenza (H5N1) (donors 4, 16, 27), and specific for H5/N1 peptides (donors 2, 27, 34, 39, 41)." (PMID 18258091, 2008).
influenza (continued). "For the different CD4+ T cell subtypes, however, the effects of HDM exposure and influenza infection showed clear interactions for most subsets, making it impossible to interpret the individual effects in the two-way ANOVA analysis." (PMID 40331962, 2025). "In human influenza research, the importance of nucleoprotein-specific CD8+ and CD4+ T cells in protection against influenza virus infection has been emphasized." (PMID 40374831, 2025). "We performed scRNA-Seq on Tfh and Tfr (by sorting total CD4+CD19–CXCR5+) cells from peripheral blood of 5 young and 7 aged individuals at baseline, day 7, and day 14 after seasonal influenza vaccination." (PMID 40036082, 2025). "For this, we analyzed TFH (CD4+CD44+CXCR5+PD-1+) cells compared to Teff (CD4+CD44+CXCR5−PD-1−) cells following LCMV, influenza, T. muris, H. polygyrus and C. rodentium infection." (PMID 40926076, 2025). "A number of animal and human studies have demonstrated the role of CD4+ and CD8+ T-cell immunity in protection against influenza infection." (PMID 40872799, 2025). "After influenza infection, chemokines such as CXCR6, direct a subset of effector CD4+ T cells to the lung airways and parenchyma, where they upregulate CD69 and CD103 to establish long-lived TRMs." (PMID 40872830, 2025). "While essential for antiviral defense, influenza-specific CD8+ and CD4+ T cells can contribute to lung injury through proinflammatory cytokine production and epithelial damage." (PMID 40872830, 2025). "While the functional profile of CD4+ TRM was largely comparable after vaccination and influenza infection, functional CD8+ T-cell responses differed between the treatment groups." (PMID 40240341, 2025). "IFN-γ-producing CD4+ T cells are essential for the optimal formation of lung CD8+ Trms, which mediate protective responses during influenza infection." (PMID 40589761, 2025). "As an experimental control, we also studied the reactivity of CD4 T cells against MP65 (Candida Albicans; C.ALB), MP1 (Influenza; H1N1) and SPIKE (SARS-CoV-2) in the AILD patients." (PMID 39880819, 2025). "In the research development of the influenza vaccine, there has been a focus on how increased CD4 and CD8 cell responses against conserved viral epitopes can confer heterosubtypic protection against influenza." (PMID 40284505, 2025). "The response to influenza, pneumococcal, and HBV vaccines is frequently suboptimal, particularly in individuals with low CD4+ nadir, inverted CD4/CD8 ratios, or metabolic comorbidities." (PMID 41153793, 2025). "Further, GI microbiota can influence the production of CD4+ and CD8+ T cells in response to influenza infection." (PMID 41012615, 2025). "Gluten-specific CD4+ T cells with the rare phenotype found in patients with CeD and in some patients with CTD were also transiently elevated during the acute phase of influenza infection." (PMID 39665304, 2025). "When further investigating the activation phenotype, expression of both CD95 and PD-1 was pronounced in the influenza compartment, whereas CD69-CD38+phenotype was seen in the global CD4+compartment and the cit-TNC compartment." (PMID 39557489, 2024). "Previous studies investigating T cell responses after intranasal immunization showed induction of protective proinflammatory lung-resident antigen-specific CD4+ and CD8+ T cells early after influenza challenge." (PMID 39283916, 2024). "The role of NP CD4+ and CD8+ T-cells in clearing the influenza infection in both human and animal models is largely supported by previous published works." (PMID 39772052, 2024). "In summary, these studies highlight the variability in influenza vaccine responses among HIV-infected individuals, with factors such as age, CD4+ cell counts, preexisting antibodies, and inflammatory monocytes influencing outcomes." (PMID 38792562, 2024). "An alternative approach is to target conserved antigens that induce CD4+ and CD8+ T-cell responses, providing the basis for a broadly protective influenza vaccine (BPIV)." (PMID 39397062, 2024).